KCNJ4 (potassium inwardly rectifying channel subfamily J member 4)
Description:
Inward rectifier potassium channels are characterized by a greater tendency to allow potassium to flow into the cell rather than out of it. Their voltage dependence is regulated by the concentration of extracellular potassium; as external potassium is raised, the voltage range of the channel opening shifts to more positive voltages. The inward rectification is mainly due to the blockage of outward current by internal magnesium. Can be blocked by extracellular barium and cesium.
Synonyms: HIR; IRK-3; IRK3; Kir2.3; HRK1; hIRK2
Tractability: Small molecule: it belongs to a druggable protein family. Antibody: its Gene Ontology location is reachable by antibodies, with high confidence; UniProt places it where antibodies can reach, with medium confidence; UniProt predicts a signal peptide or a membrane-spanning region.
Target class: Inwardly rectifying potassium channel; Potassium channels; Voltage-gated ion channel; Ion channel
Gene: Protein-coding gene on chromosome 22 (38,426,327 to 38,455,639, reverse strand). Ensembl gene ENSG00000168135.
Subcellular location: Cell membrane; Postsynaptic cell membrane; Cytoplasmic vesicle membrane
Subcellular location (Human Protein Atlas): Vesicles
Pathways (Reactome):
Neuronal System: Activation of G protein gated Potassium channels; Classical Kir channels; Inhibition of voltage gated Ca2+ channels via Gbeta/gamma subunits
Muscle contraction: Phase 4 - resting membrane potential
Gene Ontology:
Molecular function: inward rectifier potassium channel activity; PDZ domain binding; protein binding
Biological process: potassium ion import across plasma membrane; potassium ion transport
Cellular component: basolateral plasma membrane; cytoplasmic vesicle membrane; plasma membrane; postsynaptic membrane; voltage-gated potassium channel complex; membrane
Genetic constraint (gnomAD): Loss-of-function variants: 3 observed, 27.03 expected, observed/expected ratio (o/e) 0.11, 90% interval 0.05 to 0.29. The upper end of that interval is the gene's LOEUF score, 0.29, which puts it in group 1 of 6, group 1 being the genes least tolerant of losing a copy. Missense variants: 286 observed, 682.64 expected, observed/expected ratio (o/e) 0.42, 90% interval 0.38 to 0.46. Synonymous variants: 257 observed, 294.12 expected, observed/expected ratio (o/e) 0.87, 90% interval 0.79 to 0.97.
Homologues: Orthologues: chimpanzee KCNJ4 (100% identical), macaque KCNJ4 (99% identical), mouse Kcnj4 (98% identical), guinea pig KCNJ4 (98% identical), pig KCNJ4 (98% identical), rat Kcnj4 (98% identical), rabbit KCNJ4 (97% identical), tropical clawed frog kcnj4 (77% identical). Paralogues in human: KCNJ12 (64% identical), KCNJ18 (63% identical), KCNJ2 (60% identical), KCNJ14 (54% identical), KCNJ6 (43% identical), KCNJ3 (42% identical), KCNJ9 (42% identical), KCNJ5 (41% identical), KCNJ8 (38% identical), KCNJ11 (38% identical), KCNJ16 (37% identical), KCNJ1 (37% identical), and 3 more.
Diseases named in the same sentence as KCNJ4 in open-access papers:
KCNJ4 is named in the same sentence as 17 diseases in open-access papers, as found by Europe PMC text mining. Sharing a sentence is not in itself a finding about the gene and the disease. The quoted sentences say what the papers report.
lung carcinoma (4 papers, 2018 to 2023). "In small cell lung cancer (SCLC), KCNJ4 modulates cell growth, and its silencing sensitizes lung cancer cell lines to the cytotoxic effects of adriamycin, cisplatin, and etoposide." (PMID 37408210, 2023). "Kir channel subfamily J member 2 (KCNJ2 or Kir2.1) and Kir channel subfamily J member 4 (KCNJ4 or Kir2.3) have been involved in lung cancer." (PMID 37408210, 2023). "Each of the other SNPs, including KCNJ4 rs138396 and SCN2B rs7944321, appeared to have a slightly elevated risk of lung cancer in discovery and replication." (PMID 30104567, 2018).
dilated cardiomyopathy (2 papers, 2020 to 2023). Cardiomyopathy which is characterized by dilation and contractile dysfunction of the left and right ventricles. "Previous studies have shown that KCNJ4 is associated with the progression and poor prognosis of lung adenocarcinoma, dilated cardiomyopathy, and prostate cancer." (PMID 36902271, 2023).
Parkinson disease (2 papers, 2009 to 2025). A progressive degenerative disorder of the central nervous system characterized by loss of dopamine producing neurons in the substantia nigra and the presence of Lewy bodies in the substantia nigra and locus coeruleus. "Kcnj4 (or Kir2.3) has recently been linked with protection against neurodegeneration in a cell model of Parkinson's disease, although its role in the immune system is currently unknown." (PMID 19915720, 2009).
Cognitive impairment (1 paper, 2019). Abnormal cognition is characterized by deficits in thinking, reasoning, or remembering. "Among the significantly enriched signaling pathways from KEGG analysis, oxytocin signaling pathway (PATH:04921; Cacng2, Adcy1, Kcnj4, Kcnj9, Adcy8, Pik3cd, Elk1, Adcy4, Camkk2, Cacng7, Nos3, Kcnj2) may play an important role in the sevoflurane-induced cognitive impairment." (PMID 31582589, 2019).
COVID-19 (1 paper, 2023). A disease caused by infection with severe acute respiratory syndrome coronavirus 2. "Recent bioinformatic research revealed the ion channel-related gene features in COVID-19, of which the up-regulated gene, KCNJ4, was identified as the hub gene." (PMID 36902271, 2023). "Five hub genes, including GAD2, SST, TAGLN3, SYP, and KCNJ4, were further verified using the test_datasets of COVID-19, AD, and PD." (PMID 36902271, 2023).
kidney damage (1 paper, 2023). "Collectively, these results indicate that overexpression of KCNJ4 in vivo alleviates kidney damage and increases antioxidative enzyme activities by preserving mitochondrial function." (PMID 37152664, 2023).
Stroke (1 paper, 2012). Sudden impairment of blood flow to a part of the brain due to occlusion or rupture of an artery to the brain. "Htr2a, a gene heavily implicated in the post-stroke depression and Kcnj4 (excitatory neurotransmission) were also persistently upregulated in young rats." (PMID 23251410, 2012).
cancer (2 papers, 2013 to 2023). A tumor composed of atypical neoplastic, often pleomorphic cells that invade other tissues. "Both KCNJ4 and KCNJ12 belong to the inward rectifier potassium channel family, which have been linked with cancer progression and might be valuable prognostic biomarkers and potential therapeutic targets for cancers." (PMID 37152664, 2023).
KCNJ4 also shares sentences with these, for which no sentence is quoted: Alzheimer disease (1 paper); cardiovascular diseases (1); cryptococcosis (1); electrolyte imbalance (1); glioblastoma (1); infection (1); interstitial lung disease (1); lung adenocarcinoma (1); prostate carcinoma (1).